CLU (clusterin)
Diseases named in the same sentence as CLU in open-access papers (continued):
Sharing a sentence is not in itself a finding about the gene and the disease.
cancer (continued). "Clusterin (CLU) is a stress-induced chaperone that confers proliferative and survival advantages to cancer cells." (PMID 25609201, 2015). "Consistent with these accumulated findings, inhibition of CLU using OGX-011 synergistically enhances conventional as well as molecular targeted therapies in cancer preclinical models." (PMID 25138053, 2014). "The role of clusterin in cancer and neurodegeneration has been extensively studied, however little is known about its functions in the immune system." (PMID 24865838, 2014). "This study defines a novel adaptor protein function for CLU under stress conditions, and highlights how co-targeting CLU and autophagy can amplify proteotoxic stress to delay cancer progression." (PMID 25503391, 2014). "OGX-011 is a second-generation phosphorothioate antisense oligonucleotide currently in late stage clinical development that potently inhibits CLU expression and enhances the efficacy of anticancer therapies in various human cancers." (PMID 25138053, 2014). "Clusterin (CLU), a pleiotropic protein with a broad range of functions, has recently drawn much attention because of its association with cancer promotion and metastasis." (PMID 25360666, 2014). "It has already been demonstrated that silencing expression of the clusterin gene in cancer cells using small interfering RNA induces spontaneous apoptosis, reduced growth ability, and cell sensitization to genotoxic and oxidative stress." (PMID 23418433, 2013). "Several studies confirmed that CLU played an important role in cancer development and progression through promoting cell survival and migration." (PMID 23457489, 2013). "In light of CLU expression knowledge and its role in cancer, we sought new methods allowing down-regulation of the sCLU form while increasing expression of the nCLU form." (PMID 23418433, 2013). "Increased levels of CLU have been previously observed in the sera of patients with OCa, as well as those with other types of cancers." (PMID 23579955, 2013). "Here we focus on CLU expression in normal and in cancer cells after treatment with MG‐132, a peptide-aldehyde blocking proteasome function." (PMID 24073260, 2013). "Clusterin (CLU) is a stress-activated chaperone, which plays an important role in cancer development and progression through promoting cell survival." (PMID 23457489, 2013). "Three of the targets—clusterin, survivin, Bcl-2—have well-characterized roles in mechanisms which protect cancer cells from apoptosis induced by cytotoxic drugs." (PMID 22989709, 2012). "Clusterin levels are increased in a variety of cancers with broad-spectrum resistance to radiation and chemotherapy and inhibition of clusterin enhances apoptosis in xenograft models of cancer." (PMID 22989709, 2012). "In cancer clusterin inhibits apoptosis through its suppression of proapoptotic BAX and activates the PI3K/AKT cell survival pathway." (PMID 22989709, 2012). "Prognostic significance of CLU expression has been reported in different cancer types in the literature." (PMID 22185350, 2011). "Immunolocalization with anti-CLU antibody largely showed positive staining in the cytoplasm of cancer cells and occasionally positive in the nucleus." (PMID 22185350, 2011). "More recent studies suggest that antisense oligonucleotide or interfering RNAs (siRNAs) to clusterin can enhance chemosensitivity in human cancer cells." (PMID 21609464, 2011). "CLU protein is commonly up-regulated by chemotherapy and radiotherapy in cancer cells, and contributes to cancer cell resistance in vitro and in various animal models of cancer by blocking apoptosis." (PMID 22185350, 2011). "At least 50 genes in our list are already known to be regulated by DNA methylation, such as those encoding cancer antigens (a set of MAGE and GAGE), H19, S100A4, IGFBP4, UCHL1, COL1A2, CLU, FN1, and TGFBI." (PMID 19234609, 2009).
cancer (continued). "Many recent studies have reported important roles of clusterin in carcinogenesis, tumorigenesis and chemoresistance and its expression level has been shown to be deregulated in several cancers, suggesting a potential clinical use as a cancer biomarker." (PMID 19348683, 2009). "Blocking clusterin, on the other hand, reverses the drug's unwanted effects on cancer cell survival." (PMID 18078515, 2007). "Clusterin has been demonstrated to promote cancer cell survival, proliferation, and metastasis through signaling cascades such as adenosine monophosphate–activated protein kinase/mechanistic target of rapamycin/Unc-51 like autophagy activating kinase 1 and AKT/GSK3β/β-catenin pathways." (PMID 40671119, 2025). "The result suggested that BCL2L1 was a key downstream molecule of the pro-cancer effect of CLU." (PMID 40606578, 2025). "Interestingly, six genes among these (ABCB1, FGF2, CXCR4, IL6, PSMB9, and CLU), as well as UGCG, are known to be highly associated with cancer resistance to platinum-based chemotherapy." (PMID 40507922, 2025). "The dual effect of CLU silencing and curcumin-induced ROS suggests a synergistic mechanism where oxidative stress acts as a mediator of cytotoxicity, thus contributing to the inhibition of cancer cell growth." (PMID 40573993, 2025). "Whether clusterin is preferentially overexpressed in metastases to the liver and has a role in the worse outcome of patients with cancer at this site may be an interesting avenue of investigation." (PMID 40723267, 2025). "As recently explored in a comprehensive review, the potential of CLU inhibition to induce senescence, when combined with natural senolytics, could be used to accelerate the suppression of cancer cell growth." (PMID 40573993, 2025). "This suggests that androgens may control the cytoprotective and antiapoptotic role of CLU in cancer progression." (PMID 39253532, 2024). "Moreover, like other well-known mitophagy receptors such as BNIP3L and FUNDC1, CLU overexpression triggers mitophagy to clear damaged mitochondria, protecting cancer cells from cisplatin-induced stress." (PMID 38447939, 2024). "CLU is typically overexpressed during aging and cancer progression." (PMID 39253532, 2024). "Moreover, CLU interacts with LC3 to induce autophagosome biogenesis to enhance cancer cell survival." (PMID 38447939, 2024). "Similarly, the levels of CLU, which were reduced following the expression of HLA-G in the cancer cells, were found increased within the CRISPR/Cas9-mediated edited cells (left)." (PMID 39358558, 2024). "Targeting CLU represents a promising strategy for both cancer and neurodegenerative diseases." (PMID 39253532, 2024). "Therefore, further exploration of the role of CLU in therapy resistance in CRC is warranted, with consideration of factors including different cancer stages, mutation profiles and consensus molecular subtypes (CMSs) required." (PMID 38319453, 2024). "Growing evidence also reports the unique function of CLU in promoting cancer cell survival through activating an autophagy cascade, where CLU interacts with LC3 through its putative LC3-interacting region (LIR) motif, facilitating a stable LC3-ATG3 hetero-complex leading to autophagosome biogenesis." (PMID 38447939, 2024). "SEMG1, CLU and GSN have been reported to be associated with cancers." (PMID 38763993, 2024). "Such properties potentialize CLU to be a promising target in cancer therapy." (PMID 37686218, 2023). "Given that NF-κB is a key player in inflammation, clusterin may act as a molecular connection between inflammation and cancer by elevating both NF-κB and MMP-9." (PMID 37685987, 2023). "Additionally, in vitro studies have been conducted to examine clusterin expression in response to various chemotherapeutic agents and its relationship with the heterogeneity of cancer stem cell populations." (PMID 37834086, 2023). "This is of high interest since CLU is overexpressed in many cancers." (PMID 37685987, 2023).
cancer (continued). "The results suggested that CLU could act as a suppressor of tumors during the initial phase of cancer development." (PMID 37239129, 2023). "Interestingly, a totally reverse scenario is seen in kidney renal clear cell carcinoma (KIRC) and liver hepatocellular carcinoma, where CLU expression is correlated with worse cancer survival." (PMID 37239129, 2023). "In advanced stages of cancer, reduced levels of CLU could activate nuclear factor-κB (NF-κB), which is associated with inflammation, leading to the increased proliferation and invasion of cancer cells." (PMID 37239129, 2023). "This discrepancy is believed to be caused by CLU isoforms, sCLU, which has a negative effect on cancer prognosis." (PMID 37239129, 2023). "Additionally, expression levels of CLU across 33 cancer types from TCGA database were further analyzed using R package, and similar results were observed with the findings of TIMER2.0." (PMID 37686218, 2023). "Collectively, these results indicate that when the biological processes are deflected as in cancer or preecalmpsia, CLU may regulate either the aggressive behaviour of cancer cells or the EMT of trophoblast cells via regulation of MMP9 activity." (PMID 37685987, 2023). "CLU has gained increasing attention due to its paradoxical and multifunctional properties in various pathologies and is regarded as a regulator of carcinogenesis and a therapeutic target in cancers." (PMID 37686218, 2023). "Furthermore, clusterin expressed by CLU is a highly evolved and conserved glycoprotein that associates with the development of prostate, breast, pancreatic and many other cancers as reported." (PMID 37208656, 2023). "This seemed to be inconsistent with the previous reports that expression of CLU was elevated in many cancers, and this might be explained partly by the sample difference and the paradoxical property of CLU." (PMID 37686218, 2023). "Similarly, we find that cytoplasmic CLU regulates cancer metastasis through an unconventional pathway." (PMID 35626071, 2022). "This study is the first to evaluate CLU expression in a pan-cancer dataset thoroughly." (PMID 36685863, 2022). "The function of CLU in malignant tumors has been controversial in recent years." (PMID 35687899, 2022). "It has also been documented that clusterin increases the resistance of ovarian cancer to treatment, preventing drug interactions with neoplastic cells, thus preventing the induction of apoptosis and, consequently, the fight against cancer." (PMID 36071866, 2022). "Furthermore, we discovered that the predictive infiltration of CD8+ T-cell immune infiltration was significantly associated with CLU expression in PAAD and STAD cancers but inversely correlated with KIRC and THYM tumors." (PMID 36685863, 2022). "Thus, we further examined these genes and found that the mRNA expressions of C3, C5, CFB, and CLU were correlated with cancer stage and prognosis in patients with HCC." (PMID 34813686, 2022). "Furthermore, phosphorylated AKT and STAT were gradually reduced, suggesting that the oncogenic role of STMN1 in cancer metastasis was mediated by clusterin/AKT/MMP and STAT signaling." (PMID 36188577, 2022). "According to its function, CLU has been involved in many diseases that are accompanied by an impairment in protein synthesis and protein quality maintenance, including neurodegeneration, inflammatory diseases, and cancer." (PMID 34360868, 2021). "CLU acts like a stress-activated, extracellular ATP-independent small heat shock-like chaperone, whose levels are elevated during aging, cancer, and neurodegenerative disorders; recent studies have also highlighted a role for CLU in intracellular proteostasis to suppress proteotoxicity." (PMID 33744871, 2021). "CLU is a secreted glycoprotein found to be involved in neurodegeneration, aging, and cancer." (PMID 32268584, 2020).
cancer (continued). "In addition, CLU (Clusterin) is involved in anti-apoptotic processes, development of therapy resistance, induction of EMT, all associated with cancer metastasis." (PMID 33187552, 2020). "Downregulation of CLU in naïve cancers is, by far, the prevailing condition that is found." (PMID 32268584, 2020). "All of these studies indicated that CLU was a broad-resistant gene and might be a potential therapy target in cancer management." (PMID 32039450, 2020). "CLU is a heavy glycosylated secreted heterodimeric protein that is involved in many processes characterized by cellular stress, like ageing, chronic tissue inflammation, metabolic diseases, and cancer." (PMID 31885575, 2019). "However, in recent years, alternative CLU protein isoforms have been detected, most predominantly in cancer and cardiovascular research using immortalized human and/or rodent cells." (PMID 31738162, 2019). "Clusterin (CLU) is a secreted glycoprotein known to be involved both in inflammation and cancer." (PMID 31885575, 2019). "Clearly clusterin is involved in regulating cell death in neurological disease, cardiovascular disease and cancer but whether clusterin is protective or pro-apoptotic requires a more nuanced answer." (PMID 30872998, 2019). "CLU has also been proposed as a therapeutic target in cancer." (PMID 31215484, 2019). "It was also shown that CLU can regulate macroautophagy in cancer cells by inducing LC3 lipidation." (PMID 31406108, 2019). "CCL5 and CLU have previously been reported as upregulated and/or secreted in several cancer types." (PMID 31215484, 2019). "In addition, activation of STAT3 and inhibition of Bax activity via clusterin has been documented in hypothalamus, plasma, and cancer cells." (PMID 28767729, 2017). "Therefore, CLU is involved in many diseases related to oxidative stress, including neurodegenerative diseases, cancers, inflammatory diseases, and aging." (PMID 28858246, 2017). "CLU, NDRG1, CD166, S100A11 and Galectin-1 were associated with carcinoma and Galectin-3." (PMID 28701735, 2017). "Elevated CLU mRNA and protein levels have been reported in various human cancers, including prostate, breast, bladder, lung, renal, colon, ovarian, and cervical cancers." (PMID 26988917, 2016). "In addition, several publications demonstrate how CLU down‐regulation in combination with therapeutic stressors increases anti‐cancer activity." (PMID 27198502, 2016). "Therefore, understanding the mechanism of action of CLU in cancer cells is essential for the development of novel effective cancer treatments." (PMID 26988917, 2016). "Although a number of studies analyzed CLU expression in relation to tumorigenesis, the details of its biological roles and regulatory mechanisms in human cancer cells remain unknown." (PMID 26988917, 2016). "In addition, the same cancer cell lines expressed different levels of endogenous CLU protein; among these, HeLa cells had the highest CLU expression." (PMID 26988917, 2016). "Moreover, CLU mRNA and protein were found over-expressed in several human cancers such as prostate, breast, lung, kidney, ovarian, colon, and endometrial tissues." (PMID 25934174, 2015). "It has been described that CLU also exerts a critical role in cancer metastasis." (PMID 25609201, 2015). "Our above findings link CLU overexpression to cancer metastasis and indicate that CLU may play a crucial role in HCC metastasis." (PMID 25609201, 2015). "Consequently, CLU/ApoJ is one of the major targets in cancer therapy, as it is often overexpressed in cancer cells in response to cytotoxic agents, conferring resistance to therapy." (PMID 26041885, 2015). "CLU is a glycoprotein with a slightly ubiquitous tissue distribution and an apparent involvement in biological processes ranging from neurodegeneration in Alzheimer’s disease to cancer initiation and progression." (PMID 25934174, 2015). "CLU is a protective molecule by helping cells to cope with stress condition in cancer cells." (PMID 23457489, 2013).
cancer (continued). "Emerging clinical evidences as well as preclinical findings revealed that OGX-011, a CLU inhibitor, could improve the efficacy of chemotherapy through sensitizing cancer cells to drug induced apoptosis." (PMID 23457489, 2013). "CLU has an important role in tumorogenesis and progression of human cancers." (PMID 23418433, 2013). "If, however, expression of CLU isoforms with pro-apoptotic functions would be inhibited in cancer cells, this could undermine the ultimate goal of this strategy." (PMID 24073260, 2013). "The exact mechanism of clusterin overexpression in enhancing cancer metastasis is still unclear." (PMID 22799602, 2012). "The up-regulated expression of CLU in early stages of EOCa may function to suppress the biologically aggressive behavior of the cancer cells and to exert a protective function on surviving cells." (PMID 19709441, 2009). "In contrast, decreased clusterin expression by antisense or small interfering RNA (siRNA) expression enhances the chemosensitivities of various cell lines, suggesting that clusterin expression is a prominent resistance factor in cancer cells." (PMID 18078515, 2007). "There are many proteins involved in chemoresistance in cancers—one protein of notable interest is clusterin (CLU), also known as lipoprotein J, a protein strongly associated with chemoresistance and considered one of the potential targets for treatments across various cancer cell lines." (PMID 40563890, 2025). "Moreover, CLU gene expression is finely regulated by cytokines, growth factors and stress-inducing agents, leading to abnormally elevated levels of CLU in many states of cellular disturbance, including cancer and neurodegenerative conditions." (PMID 37685987, 2023). "Remarkably, when the researchers reduced CLU expressions, it disrupted the mitochondrial metabolism of the cells, leading to the accumulation of deleterious mitochondrial superoxide, thereby augmenting the sensitivity of the cancer cells to cisplatin treatment." (PMID 37239129, 2023). "Moreover, the decreased expression of CLU in the early onset of cancer progression may promote the activation of nuclear factor-κB (NF-κB) that is related to inflammatory processes and induce proliferation and invasion in advanced cancers." (PMID 34178453, 2021). "In addition, an augment in the Clusterin expression has been demonstrated in breast, ovarian, colorectal, and pancreatic cancer and that Clusterin plays an important role in the cell survival in response to chemotherapy in these cancer types." (PMID 32337254, 2020). "This increase of CLU expression might be explained by the binding of two transcription factors, heat-shock factor 1 and 2, to a particular heat-shock element present in CLU promoter named CLU element, as previously shown in human cancer cells." (PMID 31406108, 2019). "Since stress chaperone proteins like CLU, YB-1 and Hsp27 orchestrate stress response pathways to facilitate cancer cell survival, we hypothesized that TNT formation may either be regulated by these chaperones, or play roles in transporting stress chaperones between cells." (PMID 31127190, 2019). "The major function of secreted clusterin (sCLU) is protecting cells from the deleterious effects of reactive oxygen species (ROS) and is thus involved in various physiologic processes and many pathologic conditions that are relevant to ROS, including aging, cancer, and neurological disorders." (PMID 26090425, 2015). "Two genes (CLU, MAPK8) for which expression was suppressed upon GCS knock-down were also reported to promote cancer platinum-resistance." (PMID 40507922, 2025). "Moreover, colocalization statistics revealed that GDUGS-defined glucose deficiency, CXCL8 expression and macrophage distribution were significantly correlated, suggesting that cancer cell-derived IL-8 may induce CLU expression in TAMs to facilitate antioxidation in various types of cancer." (PMID 39905539, 2025).